RAB35 (RAB35, member RAS oncogene family)
Description:
The small GTPases Rab are key regulators of intracellular membrane trafficking, from the formation of transport vesicles to their fusion with membranes. Rabs cycle between an inactive GDP-bound form and an active GTP-bound form that is able to recruit to membranes different sets of downstream effectors directly responsible for vesicle formation, movement, tethering and fusion. RAB35 is involved in the process of endocytosis and is an essential rate-limiting regulator of the fast recycling pathway back to the plasma membrane. During cytokinesis, required for the postfurrowing terminal steps, namely for intercellular bridge stability and abscission, possibly by controlling phosphatidylinositol 4,5-bis phosphate (PIP2) and SEPT2 localization at the intercellular bridge. May indirectly regulate neurite outgrowth. Together with TBC1D13 may be involved in regulation of insulin-induced glucose transporter SLC2A4/GLUT4 translocation to the plasma membrane in adipocytes (By similarity).
Synonyms: RAB1C; RAY; H-ray
Tractability: Small molecule: a structure with a bound ligand is known. Antibody: UniProt places it where antibodies can reach, with high confidence; its Gene Ontology location is reachable by antibodies, with high confidence. PROTAC: ubiquitination databases record sites on it; its protein half-life has been measured.
Target class: Enzyme; Hydrolase
Gene: Protein-coding gene on chromosome 12 (120,095,094 to 120,117,502, reverse strand). Ensembl gene ENSG00000111737.
Subcellular location: Cell membrane; Membrane, clathrin- coated pit; Cytoplasmic vesicle, clathrin-coated vesicle; Endosome; Melanosome
Pathways (Reactome):
Vesicle-mediated transport: RAB GEFs exchange GTP for GDP on RABs; TBC/RABGAPs
Metabolism of proteins: RAB geranylgeranylation
Gene Ontology:
Molecular function: G protein activity; GDP binding; GTP binding; GTPase activity; phosphatidylinositol-4,5-bisphosphate binding; protein binding
Biological process: antigen processing and presentation; endosomal transport; intracellular protein localization; mitotic cytokinesis; plasma membrane to endosome transport; protein localization to endosome; cellular response to nerve growth factor stimulus; endocytic recycling; neuron projection development; Rab protein signal transduction
Cellular component: cell projection membrane; clathrin-coated endocytic vesicle; clathrin-coated pit; endosome; extracellular exosome; intercellular bridge; melanosome; plasma membrane; clathrin-coated endocytic vesicle membrane; cytosol; endosome membrane; recycling endosome membrane; clathrin-coated vesicle
Genetic constraint (gnomAD): Loss-of-function variants: 4 observed, 27.81 expected, observed/expected ratio (o/e) 0.14, 90% interval 0.07 to 0.33. The upper end of that interval is the gene's LOEUF score, 0.33, which puts it in group 1 of 6, group 1 being the genes least tolerant of losing a copy. Missense variants: 128 observed, 270.02 expected, observed/expected ratio (o/e) 0.47, 90% interval 0.41 to 0.55. Synonymous variants: 99 observed, 104.7 expected, observed/expected ratio (o/e) 0.95, 90% interval 0.8 to 1.12.
Homologues: Orthologues: chimpanzee RAB35 (100% identical), dog RAB35 (100% identical), mouse Rab35 (100% identical), zebrafish rab35b (93% identical), macaque RAB35 (93% identical), guinea pig RAB35 (92% identical), tropical clawed frog rab35 (90% identical), pig RAB35 (87% identical), rat Rab35 (85% identical). Paralogues in human: RAB1A (56% identical), RAB1B (55% identical), RAB8B (49% identical), RAB10 (48% identical), RAB13 (48% identical), RAB8A (47% identical), RAB18 (45% identical), RAB33A (44% identical), RAB3B (44% identical), RAB12 (43% identical), RAB3C (43% identical), RAB2B (43% identical), and 56 more.
Diseases named in the same sentence as RAB35 in open-access papers:
RAB35 is named in the same sentence as 54 diseases in open-access papers, as found by Europe PMC text mining. Sharing a sentence is not in itself a finding about the gene and the disease. The quoted sentences say what the papers report.
breast carcinoma (8 papers, 2014 to 2021). "Known targets of miR-720 include TWIST1 in breast cancer, Rab35 in cervical cancer, StarD13 in colorectal cancer, and CCND1 in pancreatic cancer." (PMID 33880375, 2021). "We screened the protein levels of MICAL1 and RAB35 in five breast cancer cell lines and found that those two proteins were abundantly expressed." (PMID 27430308, 2016). "Taken together, these experiments demonstrated that RAB35 was required for EGF-induced invasion in breast cancer cells." (PMID 27430308, 2016). "We also observed that MICAL1 silencing delayed the increased invasive ability of RAB35 (CA)-expressing breast cancer cells." (PMID 27430308, 2016). "Our previous work suggested a link between RAB35 activity and increased breast cancer cell migration." (PMID 27430308, 2016). "Some studies showed that Wnt5a promotes breast cancer cell migration via the Dvl2/Rab35/Rac1 signaling pathway, and Rab35 maintains cadherins at the cell surface to promote cell–cell adhesion." (PMID 26413265, 2015). "Rac1 is reported to be essential for Wnt-driven expansion and transformation of intestinal stem cells and Wnt5a promotes breast cancer cell migration via the Dvl2/Rab35/Rac1 signaling pathway." (PMID 24962779, 2014). "And Rab35 was involved in breast cancer cell migration processes and promotes cell–cell adhesion." (PMID 26413265, 2015). "Moreover, knockdown RAB35 reduced ROS level as well as P-Akt level in breast cancer cells." (PMID 27430308, 2016). "It has been found that EGF-induced breast cancer cell invasion is MICAL1-dependent, which forms complexes with RAB35." (PMID 31019460, 2019). "RAB35 is well characterized in the Wnt5a pathway, which was identified as a potent modulator of MCF-7 breast cancer cell migration." (PMID 27430308, 2016). "Our results provide evidence that MICAL1 plays an essential role in the activation of ROS/Akt signaling and cell invasive phenotype and identify a novel link between RAB35 and MICAL1 in regulating breast cancer cell invasion." (PMID 27430308, 2016). "Taken together, our results provide evidence that MICAL1 plays an essential role in the activation of ROS/Akt signaling and cell invasive phenotype and identify a novel link between RAB35 and MICAL1 in regulating breast cancer cell invasion." (PMID 27430308, 2016). "Taken together, these experiments demonstrated that both RAB35 and MICAL1 were required for ROS generation in breast cancer cells." (PMID 27430308, 2016). "In conclusion, results obtained in this study clearly establish a new mechanistic connection between RAB35 and MICAL1 in the context of ROS generation, which could be essential in promoting cell migration and invasion during breast cancer cell metastasis." (PMID 27430308, 2016). "Collectively, these data indicate that the activation of RAB35/MICAL1 may facilitate ROS generation, which leading to PI3K/Akt signaling activation and breast cancer cell invasion." (PMID 27430308, 2016). "Although the current study has contributed to the mechanistic understanding the role of MICAL1 in breast cancer cell migration and invasion, the issue as to how RAB35 precisely regulates MICAL1 in breast cancer cells is unlikely to be settled in this paper." (PMID 27430308, 2016). "Moreover, we determine a novel link between RAB35 and MICAL1 in regulating EGF-induced breast cancer cell invasion." (PMID 27430308, 2016). "Although RAB35 could recruit different effectors to perform specific biological process, it remains unclear whether and if so, the biological relevance of RAB35 binding to MICAL1 in breast cancer cells." (PMID 27430308, 2016).
cyst (4 papers, 2016 to 2021). A sac-like closed membranous structure that may be empty or contain fluid or amorphous material. "Silencing of Rab35 resulted in loss of apical bulkheads and lumen anisotropy, leading to cyst formation." (PMID 34328499, 2021). "The death of early spermatocytes caused by loss of Par complex function in somatic cyst cells also required function of the small GTPase Rab35." (PMID 30918053, 2019). "Cdc42 silencing caused dilated spherical lumina; however, Rab35 knock-down yielded the most striking phenotype, causing the appearance of epithelial tubes (white arrowhead) and large cyst-like structures (yellow arrowhead) compared with control (Luciferase, siLuc)." (PMID 34328499, 2021). "During the initial phases of cyst development, IRSp53 and RAB35 were enriched along the opposing cell–cell membrane prior to the arrival of PODXL." (PMID 32665580, 2020). "The stage-specific death of spermatocytes observed requires action of the small GTPase Rab35 in cyst cells, suggesting participation of the recycling endosome in the mechanism that leads to non-autonomous germ cell death." (PMID 30918053, 2019). "Death of the spermatocytes is dependent on function in cyst cells of the recycling endosome small GTPase Rab35, which is reminiscent of how stretch follicle cells promote death of nurse cells in maturing eggs chambers in the ovary." (PMID 30918053, 2019). "We show that Rab35 acts either downstream or in parallel to JNK pathway activation in cyst cells that have lost Par complex function to kill neighboring spermatocytes." (PMID 30918053, 2019). "It is possible that cyst cells promote germ cell death as a consequence of Rab35 activity by engulfment of the spermatocytes, similar to other examples of somatic cell-induced germ cell death in the ovary and other organisms." (PMID 30918053, 2019). "Here we propose that Rab35 acts as a molecular tether that captures PODXL-containing vesicles around the cytokinetic bridge of the cyst-founding cell." (PMID 27040773, 2016). "Using 3D cultures of renal MDCK cells (cysts), we found that the Rab35 GTPase plays a crucial role in polarity initiation and apical lumen positioning during the first cell division of cyst development." (PMID 27040773, 2016). "The same cyst-to-cyst variability is observed in Rab35-depleted cysts, until internalized PODXL is fused back to the ECM-facing membrane." (PMID 27040773, 2016). "Perhaps Rab35 is involved in the recycling of a similar receptor in cyst cells in the testis?" (PMID 30918053, 2019). "The involvement of Rab35 in promoting death of spermatocytes following cyst cell depolarization suggests that trafficking of a signal to the cellular membrane may be required for the non-autonomous germ cell death." (PMID 30918053, 2019). "To test whether the interaction between PODXL and Rab35 was essential for normal cyst polarity, we designed a C-terminal mutant of PODXL unable to bind Rab35." (PMID 27040773, 2016). "We next addressed whether inversion of polarity upon Rab35 depletion occurred already in the initial steps of cyst development." (PMID 27040773, 2016). "Thus, a PODXL mutant unable to interact with Rab35 triggers inversion of cyst polarity from the two-cell stage by preventing fusion of PODXL vesicles at the first cell–cell interface, exactly as observed after Rab35 depletion." (PMID 27040773, 2016). "In one, activation of the JNK pathway in cyst cells that have lost function of the Par complex is required for spermatocyte death, perhaps via production of a pro-death or pro-mitotic signal that is then carried to the plasma membrane that faces the germline by Rab35." (PMID 30918053, 2019). "Thus, both depletion and inactivation of Rab35 lead to defects in cyst development." (PMID 27040773, 2016).
cyst (continued). "Another possibility is that Rab35 acts in parallel to signaling events downstream of JNK pathway activation, perhaps promoting phagocytosis of the dying spermatocytes by cyst cells that have lost function of the Par complex." (PMID 30918053, 2019). "Importantly, replacing endogenous PODXL with GFP-PODXL V496A/Y500A was sufficient to invert cyst polarity, without the need to deplete Rab35 (arrow)." (PMID 27040773, 2016).
hepatocellular carcinoma (4 papers, 2019 to 2025). A malignant tumor that arises from hepatocytes. "It has been reported that lncRNA HOX transcript antisense RNA (HOTAIR) promotes exosome secretion of hepatocellular cancer cells by regulating Ras-Related Protein Rab-35 (Rab35) and Synaptosome Associated Protein 23 (SNAP23)." (PMID 41551597, 2025). "In addition, RAB35 was identified as a binding protein of lncRNA HOTAIR and its expression was positively regulated by RNA HOTAIR, accelerating the metastasis of hepatocellular carcinoma cancer cells." (PMID 34500436, 2021).
Parkinson disease (4 papers, 2016 to 2025). A progressive degenerative disorder of the central nervous system characterized by loss of dopamine producing neurons in the substantia nigra and the presence of Lewy bodies in the substantia nigra and locus coeruleus. "Disruption of circulating Rab35 has been linked to some types of neurological disease, such as Parkinson's disease." (PMID 34926703, 2021). "The most common cause of familial Parkinson’s disease is linked to mutations in the leucine rich-repeat kinase 2 (LRRK2) protein that phosphorylates Rab10, Rab8a, Rab12 and Rab35." (PMID 40801573, 2025). "AMPK, PI3K and PKC are all phosphorylation kinases and Rab35 has been shown to be phosphorylated at Thr72 by LRRK2 in the process of Parkinson’s disease." (PMID 35754325, 2022). "To demonstrate that an increase of Rab35 levels is a specific feature of PD, we examined the serum level of Rab35 in patients affected with non-parkinsonism CNS diseases, including Alzheimer's disease (AD), spinocerebellar ataxia (SCA) and Huntington's disease (HD)." (PMID 27509057, 2016).
Alzheimer disease (3 papers, 2016 to 2023). A progressive, neurodegenerative disease characterized by loss of function and death of nerve cells in several areas of the brain leading to loss of cognitive function such as memory and language. "In fact, associations between RAB35 and neurodegenerative diseases, such as Parkinson’s disease and Alzheimer’s disease, have recently emerged." (PMID 37085665, 2023). "Our proteomics data showed a significant decrease in Alzheimer’s disease-related factors LRP1 and presenilin in RAB35-deficient hippocampus." (PMID 37085665, 2023).
cervical cancer (3 papers, 2015 to 2021). A primary or metastatic malignant neoplasm involving the cervix. "Our results show that miR-720 promotes cell migration in cervical cancer cells by directly targeting Rab35." (PMID 26413265, 2015). "Targeting the miR-720/Rab35 axis is therefore a promising therapeutic strategy for cervical cancer treatment." (PMID 26413265, 2015). "The results showed that the small GTPase, Rab35, is a direct functional target of miR-720 in cervical cancer HeLa cells." (PMID 26413265, 2015). "The newly identified miR-720/Rab35 axis provides a molecular mechanism for abnormal cell migration in cervical cancer cells via its effects on the expression of an epithelial marker, E-cadherin, and a mesenchymal marker, vimentin." (PMID 26413265, 2015). "In cervical cancer cells, miR-720 negatively regulates Rab35 and promotes cell migration." (PMID 30524285, 2018). "Firstly we further confirmed whether the mRNA and protein expression levels of Rab35 could have been regulated by miR-720 in cervical cancer HeLa cells." (PMID 26413265, 2015). "Our previous studies have shown that in non-small cell lung cancer and cervical cancer cell lines, EGF stimulation can promote intracellular Rab35 activity, thereby promoting tumor cell migration or proliferation." (PMID 30524285, 2018).
lung carcinoma (3 papers, 2018 to 2024). "This study reveals that except Rab7a, five Rab proteins, Rab8a, Rab11b, Rab27a, Rab35, and Rab37, were highly expressed in the purified AP of lung cancer cells (CL1‐5‐Q89L) with a high secretory tendency (Q) (column 4 vs. column 3)." (PMID 38804615, 2024). "In lung cancer cells, Rab35 was found to act as downstream of EGF to promote the formation of RUSC2-GIT2 complex, leading to directed cell migration." (PMID 30524285, 2018). "Our previous studies have demonstrated that EGF can stimulate Rab35 activation in lung cancer and ovarian cancer cells." (PMID 30524285, 2018).
oculocerebrorenal syndrome (3 papers, 2016 to 2021). Oculocerebrorenal syndrome of Lowe (OCRL) is a multisystem disorder characterized by congenital cataracts, glaucoma, intellectual disabilities, postnatal growth retardation and renal tubular dysfunction with chronic renal failure. "A recent report indicates that Rab35 has a role in the recruitment of Oculocerebrorenal Syndrome of Lowe (OCRL), an Inositol Polyphosphate 5-Phosphatase, to newly formed endosomes." (PMID 27261256, 2016). "The Rab35 effector and lipid phosphatase OCRL (Oculocerebrorenal Syndrome of Lowe Inositol Polyphosphate-5-Phosphatase) is required downstream of Rab35 for the retrograde trafficking of mannose-6-phosphate receptors." (PMID 34876559, 2021).
Chlamydia infection (2 papers, 2022 to 2023). "Our study found RAB35 to be significantly associated with the ability to resolve a Chlamydia infection." (PMID 35510793, 2022).
colorectal cancer (2 papers, 2021 to 2022). A primary or metastatic malignant neoplasm that affects the colon or rectum. "This study indicates that TRX2 suppresses HCT116 colorectal cancer cell migration in a Rab35-dependent manner and that exosome-mediated TRX2 inhibition inhibits cell migration, which provides new ideas for the clinical treatment of CRC." (PMID 35743001, 2022).
gastric cancer (2 papers, 2017 to 2018). A primary or metastatic malignant neoplasm involving the stomach. "In summary, we confirmed that EGF-induced activation of Rab35 in gastric cancer cells is regulated by DENND1A in this study." (PMID 30524285, 2018). "In this study we demonstrated for the first time that EGF stimulates EGFR and activates Rab35 via DENND1A in gastric cancer cells." (PMID 30524285, 2018). "In the process, Rab35 undertakes the stimulation and further promotes the migration and invasion of gastric cancer cells through its various downstream signaling molecules." (PMID 30524285, 2018). "Consistent with these research results, our study in gastric cancer also showed that EGF stimulation can also promote the activation of Rab35, and thus promote BGC823 cells migration." (PMID 30524285, 2018). "In view of this, our studies in gastric cancer have shown that DENND1A exerts GEF action during the activation of Rab35 stimulated by EGF, and through its interaction with Grb2, it can regionally recruit activated Rab35 and then promote the migration of tumor cells." (PMID 30524285, 2018). "These all suggest that Rab35 activated by DENND1A may play an important role in the development of gastric cancer." (PMID 30524285, 2018). "Further experimental results show that erlotinib pretreatment also prevented EGF-induced Rab35 activity in HeLa cells as well as in the gastric cancer cell line SGC-7901 (data not shown)." (PMID 29018350, 2017). "Currently, Rab35 has not been reported in gastric cancer metastasis." (PMID 30524285, 2018). "Therefore, the main purpose of this study is to observe the changes of Rab35 activity and its relationship with gastric cancer cell migration stimulated by EGF and to determine what kind of GEF is involved in the changes of Rab35 activity in gastric cancer cells and its possible mechanism." (PMID 30524285, 2018). "However, the expression of these GEFs for Rab35 in gastric cancer tissues is not yet clear." (PMID 30524285, 2018). "In gastric cancer cells, the mechanism by which GEF participates in Rab35 regulation is not clear." (PMID 30524285, 2018).